OFCC1 (orofacial cleft 1 candidate 1 (pseudogene))
Synonyms: MRDS1; OFCC1P; Opo
Gene: Transcribed unitary pseudogene on chromosome 6 (9,596,297 to 9,939,349, reverse strand). Ensembl gene ENSG00000181355.
Diseases named in the same sentence as OFCC1 in open-access papers:
OFCC1 is named in the same sentence as 11 diseases in open-access papers, as found by Europe PMC text mining. Sharing a sentence is not in itself a finding about the gene and the disease. The quoted sentences say what the papers report.
orofacial cleft (4 papers, 2010 to 2020). A disorder of facial skeleton that is characterized by cleft lip and/or cleft palate that result in feeding, speech and hearing problems caused by failures during development. "The gene Ofcc1 in the mouse, AABR07027339.1 in the rat and ENSOCUG00000016635 in the rabbit are consistent with the human pseudogene OFCC1 and belong to same family with a gene potentially causal for orofacial cleft in humans." (PMID 32927891, 2020). "After an initial study suggesting that the OFCC1 gene led to orofacial clefts, it was later linked to schizophrenia." (PMID 26903887, 2016). "Finally, a translocation breakpoint in OFCC1 has been associated with orofacial clefting." (PMID 20585627, 2010). "The human ortholog of this gene, MRDS1/OFCC1, is a potentially causal gene for orofacial cleft, as well as a susceptibility gene for schizophrenia, a devastating mental illness." (PMID 22242126, 2011). "OFCC1 is also a positional candidate gene for orofacial cleft (OFC1, OMIM119530)." (PMID 22242126, 2011). "Although we cannot rule out the possibility that abrogated MRDS1/OFCC1/Mrds1/Ofcc1 is insufficient to cause craniofacial abnormalities, the simplest explanation for the current observation is that MRDS1/OFCC1 is not a causal gene for orofacial cleft seen in subjects with a chromosomal break at 6p24." (PMID 22242126, 2011).
cleft lip (2 papers, 2015 to 2023). Congenital defect in the upper lip where the maxillary prominence fails to merge with the merged medial nasal prominences. "One of the three cases with deletion of the OFCC1 gene showed bilateral cleft lips, supporting the association." (PMID 26174853, 2015). "The region R7 contains the OFCC1 gene that has been associated with isolated cleft lip with or without cleft palate (OFC1; OMIM %119530)." (PMID 26174853, 2015). "The gene OFCC1 (ofc1 candidate gene 1, MIM*614287), located at position 9,707,990–9,939,582 and shared by two of the three individuals with a cleft lip and palate in our cohort, has been proposed to be possibly related to this feature." (PMID 36964621, 2023).
schizophrenia (2 papers, 2011 to 2014). A major psychotic disorder characterized by abnormalities in the perception or expression of reality. "In contrast to results from animal studies, we found an association between schizophrenia and MRDS1/OFCC1 in a Japanese cohort." (PMID 22242126, 2011). "In the human study, we have found evidence of a genetic association between the MRDS1/OFCC1 gene and schizophrenia in a Japanese sample." (PMID 22242126, 2011). "Finally, future analysis of our Mrds1/Ofcc1-KO mice could be valuable in deciphering the mechanism of high γ-glutamyl transpeptidasemia and its possible relationship to schizophrenia." (PMID 22242126, 2011). "A subset of these genes has been implicated in other neurobehavioral disorders including depression (SLIT3), epilepsy (CLCN2, PRICKLE1), intellectual disability (AP4M1), schizophrenia (WDR60), and Tourette syndrome (OFCC1)." (PMID 24410847, 2014). "The positive association of schizophrenia with DTNBP1 has been replicated in independent studies, but association with the MRDS1/OFCC1 gene has not been tested in other ethnic populations." (PMID 22242126, 2011).
Tourette syndrome (2 papers, 2014 to 2024). A neurologic disorder caused by defective metabolism of the neurotransmitters in the brain. "Notably, risk variants in the OFCC1 gene, down-regulated in some of the analyzed Autism Spectrum Disorder datasets, have been previously linked to ASD and other neurobehavioral disorders such as Tourette syndrome." (PMID 39727940, 2024).
cancer (2 papers, 2021 to 2026). A tumor composed of atypical neoplastic, often pleomorphic cells that invade other tissues. "Currently, there is no reported association between OFCC1, Syngr3, CCDC160 and cancer." (PMID 34026368, 2021).
OFCC1 also shares sentences with these, for which no sentence is quoted: autism spectrum disorder (1 paper); depression (1); epilepsy (1); Intellectual disability (1); mental illness (1); Parkinson disease (1).